MUC5AC (mucin 5AC, oligomeric mucus/gel-forming)
Diseases named in the same sentence as MUC5AC in open-access papers (continued):
Sharing a sentence is not in itself a finding about the gene and the disease.
cancer (124 papers, 2006 to 2025). A tumor composed of atypical neoplastic, often pleomorphic cells that invade other tissues. "MUC5AC is considered to be a marker for early pancreatic neoplasms and is associated with cancer progression." (PMID 40699746, 2025). "Abnormal mucin glycoproteins have been implicated in various cancers, with decreased MUC5AC expression in gastric being associated with malignant transformation." (PMID 38398089, 2024). "Knock-down of MUC5AC restored the cell malignant phenotypes caused by circRABL2B inhibition, indicating that MUC5AC was a major mediator of circRABL2B's anti-cancer function." (PMID 37324942, 2023). "They found that MUC5AC expression was significantly higher in IPMN-associated carcinoma than in low-grade IPMN." (PMID 37470859, 2023). "MUC5AC has been previously associated with different types of cancer both as a good and bad prognostic marker." (PMID 35159257, 2022). "Nevertheless, poorly differentiated carcinoma was observed in Slc26a9fl/fl/Atp4b-Cre mice at 18 months, which was accompanied by loss of MUC5AC and Claudin 18.2 expression compared with that in Slc26a9fl/fl littermates." (PMID 35426084, 2022). "Ensituximab (Neo-102), a novel chimeric monoclonal antibody, binds to an aberrantly glycosylated cancer-associated MUC5AC variant and is able to activate the immune system to exert a cytotoxic T-lymphocyte response." (PMID 33373033, 2021). "Further mutations in cancer-related genes included Nav3 (V1129L), Cenpf (D1327E), Muc5ac (A429P), Mpp7 (Q158R), Gas1 (G326R), Maged2 (A473S), Dusp1 (C24R), Ros1 (W1875C), Polr2a (M1102I), Rragd (L385P), and Hoxa9 (insertion of “G” in UTR)." (PMID 32793490, 2020). "The change of MUC5AC expression was demonstrated to be associated with poor prognosis of malignant tumors." (PMID 28938681, 2017). "However, further studies are needed to elucidate the association between MUC5AC and the aggressive behavior of AoV cancer." (PMID 38893239, 2024). "Thus, despite the differences in cutoff values, the detection of any positive expression of MUC5AC in patients with AoV cancer is associated with worse survival outcomes." (PMID 38893239, 2024). "Moreover, the specific MUC5AC protein expression is associated with aggressive cancers and worse overall survival." (PMID 34475526, 2022). "Interestingly, although MUC5AC positive cancers are associated with significantly worse overall survival in patients, MUC2 cancers show a much more indolent phenotype." (PMID 34475526, 2022). "Importantly, the target for the NPC-1 (TAA) was later identified as an aberrantly glycosylated MUC5AC variant (cancer-specific MUC5AC) that is different from native MUC5AC." (PMID 34205412, 2021). "Analysis of 230 GC patients and 328 controls showed the MUC5AC-u repetitive region was highly polymorphic, with eight different alleles (plus a 0.9 kb allele in the cancer tissue from one GC patient) being present in a Han Chinese population from northeastern China." (PMID 24887023, 2014). "The significance of Muc1, Muc4, and Muc5AC has been highlighted in the progression of cancer using a KrasG12D;Pdx1-Cre murine model." (PMID 40699746, 2025). "For example, inhibiting O-glycosylation of MUC1 or MUC5AC sensitizes cancer cells to chemotherapy and radiotherapy." (PMID 40655139, 2025). "TFF1, TFF2, and MUC5AC were highly expressed in foveolar cells-1 and -2, intestinal metaplasia cells, and cancer cell cluster EAC-01." (PMID 40925382, 2025). "Two cases of superficially invasive carcinomas showed surface predominant MUC5AC expression and deep layer MUC6 expression, similar expression to that seen in normal gastric mucosa." (PMID 39164422, 2025). "The dysregulation of MUC5AC expression shows varied correlations with survival and prognosis in different cancers." (PMID 38893239, 2024).
cancer (continued). "In our study, we attempted to explore the prognostic importance of these mucins in AoV cancer, confirming previously known factors, such as T stage, N stage, and lymphovascular invasion, along with identifying MUC5AC as a prognostic factor." (PMID 38893239, 2024). "Multiple studies have suggested that MUC1 expression increases as gallbladder lesion severity progresses from hyperplasia to carcinoma in situ, whereas MUC5AC expression decreases with escalating lesion severity." (PMID 38786750, 2024). "The patients with AoV cancer presenting a positive MUC5AC expression had a notably shorter OS than those with negative expression levels (p = 0.004)." (PMID 38893239, 2024). "Study methods were variable regarding cancer subtypes, expression positivity thresholds, and MUC5AC glycoforms." (PMID 36672382, 2023). "MUC5AC has also been studied in diseases including malignancies of the lungs, stomach, colon, breast, pancreas, and other organs." (PMID 36672382, 2023). "Although there are ample differences in study methods such as the cancer subtype analyzed, MUC5AC glycoform targeted, or positivity threshold selected, there is no clear association between these factors and the variability of the evidence." (PMID 36672382, 2023). "Reported MUC5AC tissue expression in BTC varies widely, with some associations based on cancer location (e.g., perihilar vs. peripheral ICC)." (PMID 36672382, 2023). "In GC, VSIG1 can be considered an indicator of gastric phenotype carcinomas, where carcinogenesis is mainly driven by MUC5AC." (PMID 37240039, 2023). "In cancers, 320 (67.2%) of the 476 interpretablesamples show weak to strong membranous and cytoplasmic MUC5AC staining." (PMID 35764407, 2022). "According to our classification, positive cases included 97 (5.8%) cancers with weak, 63 (3.8%) with moderate, and 101 (6.0%) with strong MUC5AC staining." (PMID 33373033, 2021). "Two main studies have used recombinant chimeric NPC1 antibodies prepared in Chinese hamster ovary cells (NPC-1C) to identify cancer-specific MUC5AC." (PMID 34205412, 2021). "The vast majority of MUC5AC positive cancers were derived from organs where at least some cells normally express MUC5AC." (PMID 34547930, 2021). "Histologic patterns suggestive for progression of some cytokeratin 7 and/or MUC5AC-positive metaplastic lesions into cancer of the same phenotype were also observed." (PMID 33963925, 2021). "In summary, our data provide a systematic overview of MUC5AC expression in human cancers using a standardized approach across all tissues and demonstrate potential diagnostic applications." (PMID 34547930, 2021). "Its high abundance in cancer is probably associated with changes in mucins expression associated with CRC progression, including an upregulation of MUC5AC and downregulation of MUC2, and even the loss of its expression in some patients." (PMID 34209683, 2021). "MUC5AC expression is also seen in carcinomas arising from tissues that completely lack positive MUC5AC immunostaining under physiological circumstances." (PMID 34547930, 2021). "Studies have suggested that secretory mucin MUC5AC is overexpressed in several cancers and its up-regulation favors progression-free as well as cancer-specific survival of intermediate stages II and III of CRC patients." (PMID 32098629, 2020). "For cancer related genes, Nav3, Cenpf, Muc5Ac, Mpp7, Gas1, MageD2, Dusp1, Ros, Polr2a, Rragd, Ros1, and Hoxa9 are mutated." (PMID 32793490, 2020). "The increase in MUC1 expression is consistent with that observed in cancer cell lines and the decrease of MUC5AC expression is in agreement with previous results in lung epithelial cells." (PMID 32033337, 2020). "It supports the MUC5AC functions as an immunosuppressive agent and plays a key role in the escape of carcinoma cells from immunosurveillance." (PMID 32028958, 2020).
cancer (continued). "It has been shown previously that expression of mucin genes (including MUC1, MUC2, MUC3, MUC4 and MUC5AC) is regulated by DNA methylation at promoter regions in cancer cell lines." (PMID 27283771, 2016). "In agreement with our data, a small study analyzing 41 cancer and 41 normal mucosa specimens as well as 21 metastatic lymph nodes also found that patients with tumors expressing MUC5AC had longer disease-free and of overall survival." (PMID 27298226, 2016). "Previously we showed that most cancer-precursor cysts, termed mucinous cysts, produce abnormal glycoforms of the proteins MUC5AC and endorepellin." (PMID 27992432, 2016). "In Case 2, the neoplastic and carcinoma cells were strongly positive for MUC5AC and MUC6 but only focally positive or negative for MUC1, MUC2, CDX2, CK7, and CK20, suggesting that this immunophenotype was compatible with the gastric type." (PMID 27656307, 2016). "It is noted that the void-volume peaks obtained from other cancer cell lines known to secret MUC5AC, such as HT-29, LS 174T, SW1990, CFPAC-1, and Calu-3, were all tested positive for reactivity with hPAM4." (PMID 25595893, 2015). "When we examined the MUC5AC-u repetitive region length in DNA from normal and cancer tissues from some GC patients, we found two examples of length alterations." (PMID 24887023, 2014). "In this study, length polymorphisms in a complicated repetitive region adjacent to MUC5AC promoter were assessed in 230 patients with GC and 328 cancer-free controls." (PMID 24887023, 2014). "Previous work using this method showed that the mucins MUC1, MUC5AC, and MUC16 are major cancer-associated carriers of the CA 19-9 antigen in the blood." (PMID 22220206, 2011). "One of the cancer samples that showed negligible signal at any antibody using CA 19-9 detection (sample LC3607) showed clear signal at the MUC5AC antibody using detection with BPL." (PMID 22220206, 2011). "Next, we investigated production of MMP-3 and alpha 3-integrin proteins by cancer cells, resulting in higher expression level of these proteins by parental cells compared with MUC5AC suppressed cells." (PMID 20492722, 2010). "In the present study, all of the markers except MUC-5AC showed greater expression in the IT than in the DT carcinomas." (PMID 18266006, 2008). "In an immunohistochemical study using non-tandem repeat antibodies, there was de novo expression of MUC5AC in 23/36 carcinomas." (PMID 16409634, 2006). "Importantly, MUC5AC expression emerged as an independent predictor of poor survival in AoV cancer, along with lymph node metastasis, as determined by multivariate analysis." (PMID 38893239, 2024). "Our study highlights MUC5AC as an independent prognostic indicator for AoV cancer." (PMID 38893239, 2024). "Further research is necessary to validate the clinical impact of MUC5AC in AoV cancers." (PMID 38893239, 2024). "Moreover, our study revealed that MUC5AC expression is significantly related to aggressive clinicopathological features of AoV cancer, such as lymph node metastasis." (PMID 38893239, 2024). "Healthy human pancreas ducts are reported to have MUC5B expression and lack MUC5AC expression, but both may be present in diseased pancreas (e.g. cancer)." (PMID 37349833, 2023). "Further, in the validation set, it was confirmed that MUC5AC is predominantly present in high-risk IPMN patients, suggesting that exosome-derived mucins could be potential biomarkers for early cancer detection." (PMID 36980526, 2023). "Similarly, the deregulation of secretory mucin MUC5AC expression correlates differently with survival and disease prognosis in various cancers." (PMID 36980526, 2023). "There are a wide range of study methods (e.g., positivity thresholds), cancer subtypes, and MUC5AC glycoforms analyzed; however, it is unclear whether these differences could explain any of the variation in reported prognostic relevance." (PMID 36672382, 2023).
cancer (continued). "However, Cluster 7 and Cluster 3, which were abundant in cancer-adjacent tissues, showed high expressions of Muc5ac and Muc6, respectively (markers of pit mucous cells and gland mucous cells, respectively)." (PMID 36612160, 2022). "It was, thus, the aim of this study to analyze a large sample set to betterunderstand the relationship of MUC5AC expression and parameters of canceraggressiveness, and to determine whether MUC5AC expression might be linked to MSI inpancreatic cancer." (PMID 35764407, 2022). "The role of MUC5AC expression in cancer is not fully understood." (PMID 35764407, 2022). "However, both in dMMR and in pMMR cancers, MUC5AC expression is unrelated to aggressive cancer phenotype." (PMID 33373033, 2021). "In the subgroups of dMMR and pMMR cancers, MUC5AC expression was unrelated to pT and pN status." (PMID 33373033, 2021). "Approximately 80% of cancer patients had higher levels of NPC-1C-reactive MUC5AC." (PMID 34205412, 2021). "MUC5AC expression was informative in 1667 (92%) of the 1,812 arrayed cancers in our IHC analysis." (PMID 33373033, 2021). "However, GAFG that is positive for MUC5AC differentiates to the foveolar epithelium, and thus, shows epithelial changes and meets the criteria for the diagnosis of carcinoma." (PMID 31165461, 2019). "Importantly, aberrant and mislocalized expression of MUC5AC mucin in adenomas and carcinomas has been reported, as well as modification of mucins glycosylation patterns during colonic carcinogenesis." (PMID 29666615, 2018). "In this study, the expression of MUC5AC was significantly higher in ccRCC tissues compared with the corresponding tissue adjacent to carcinoma, suggesting that MUC5AC may be involved in the development and progression of ccRCC." (PMID 28938681, 2017). "Since SOX2 is associated with gastric differentiation we studied whether this was maintained in cancer, using MUC5AC as a gastric marker." (PMID 25300947, 2014). "The present immunohistochemical study found that MUC5AC was immunopositive in the hyperplastic, dysplastic and carcinoma regions of the polyps; while this marker was detected in the hyperplastic and dysplastic areas only, but not in the carcinomatous component, in one case." (PMID 24765156, 2014). "In this context, it was important to examine the possibility that γ-secretase inhibition could differentially affect MUC2 and MUC5AC expression by cancer cells." (PMID 23409082, 2013). "Unlike the less consistent expression patterns of MUC1, MUC6 and MUC5AC in normal and cancer tissues, MUC2 levels were always measured low in normal endometrial and cervical tissue, and elevated MUC2 expressions were specifically found in various neoplastic lesions." (PMID 22417007, 2012). "We found that the mucins MUC1, MUC5AC, and MUC16 are indeed major cancer-associated carriers of CA 19-9, but because of the diversity among patients in the proteins that carry CA 19-9, the detection of CA 19-9 on any single protein did not out-perform total CA 19-9." (PMID 22220206, 2011). "Although we could not find reports about relationship of VEGF with MUC5AC, our results suggested that MUC5AC might have potential to regulate VEGF expression by cancer cells themselves." (PMID 20492722, 2010). "All the markers except MUC-5AC showed higher expression in IT than DT carcinomas (p < 0.05)." (PMID 18266006, 2008). "Although the mechanism by which MUC5AC affects AoV cancer progression remains unclear, it is believed to regulate cell–cell and cell–stroma interactions, thereby enhancing the invasiveness and metastatic behavior of various cancer types." (PMID 38893239, 2024). "MUC5AC is normally expressed by airway epithelial cells in response to stresses such as exposure to cigarette smoke and allergens; however, it is also highly overexpressed in several cancers, including LUAD, potentially contributing to Kras mutant-driven LC9–11,16,30." (PMID 38825648, 2024).
cancer (continued). "Therefore, MUC5AC expression in preoperative biopsies can serve as a useful biomarker for extensive lymph node dissection and prognostic evaluation in patients with AoV cancer." (PMID 38893239, 2024). "The differences observed in MUC5AC expression in our study may reflect the use of normal primary cells versus immortalized cancer lines, the use of different virus preparations and MOIs, different concentrations and/or preparations of poly(I:C) and a difference between cell donors." (PMID 32599823, 2020). "As certain variable number of tandem repeat polymorphisms are reported to exert dual, conflicting effects on the risk and prognosis of cancer, we compared the age at onset and clinical stages between GC patients with and without MUC5AC-u repetitive regions of 1.4, 1.8 or 2.3 kb separately." (PMID 24887023, 2014). "As repetitive regions of DNA are unstable in various human malignancies, including GC, we next determined whether the hypervariable MUC5AC-u repetitive regions differed in length between cancer, para-carcinoma and surrounding normal tissues from 36 GC patients." (PMID 24887023, 2014). "For instance, in LCRC, researchers have identified a subgroup of cancer cells enriched for genes involved in maintaining of the gut lining (e.g., TFF1, TFF2, AGR3, MUC5AC)." (PMID 41450739, 2025). "The current chapter shows the importance of various mucins (MUC1, MUC3A, MUC4, MUC4β, MUC5AC, MUC5B, MUC7, and MUC16) and their mucin-bound carrier proteins in different cancers." (PMID 40699805, 2025). "Next, we analyzed the correlation between the expression levels of MUC2, MUC5AC, and MUC6 and various clinicopathological factors in the 68 patients with AoV cancer." (PMID 38893239, 2024). "MUC1, MUC2, MUC5AC, and MUC6 were the most commonly analyzed mucins across cancer types according to this literature review." (PMID 39886661, 2024). "AoV cancer typically exhibits a desmoplastic stroma and commonly expresses MUC1, MUC5AC, MUC6, and MUC2." (PMID 38893239, 2024). "MUC5AC stimulates signaling through integrin avb5, pSrc (Y416), and pSTAT3 (Y705), which upregulates KLF4 and increases the tumorigenic propensity of cancer stem cells." (PMID 37239940, 2023). "Among MUC proteins, MUC1, MUC2, MUC4, MUC5AC, MUC6, MUC13, and MUC16 have been demonstrated to be involved in cancer progression." (PMID 37324940, 2023). "MUC1, MUC2, MUC5AC and MUC6 were the most commonly analysed mucins across all three cancer types according to this literature review." (PMID 37958425, 2023). "MUC1, MUC2, MUC4, MUC5AC, and MUC6 are currently the most widely covered in the literature regarding their role in the progression from normal colonic tissue to cancer." (PMID 36900282, 2023). "For instance, MUC1, MUC5AC, MUC17, and CA19-9 are expressed in carcinomas originating from the conventional pathway, whereas carcinomas originating from serrated pathways do not express these mucins." (PMID 36980526, 2023). "In the first step, supernatant fluid from various cancer cell lines (pancreas, colon, lung, squamous cell carcinoma) was admixed with NPC-1C Mab in a competitive ELISA assay (using MUC5AC antigen-coated microtiter plates)." (PMID 34205412, 2021). "Immunohistochemically, the cancer cells exhibited strong expression of “intestinal” differentiation markers, including CDX2, MUC2, and MUC5AC." (PMID 34487254, 2021). "MUC5AC, when included in the same model in place of CK7, lost predictive power of cancer-specific survival (HR 1.20, 95% CI: 0.49–2.91, p=0.692)." (PMID 33963925, 2021). "Recently, we observed that secretory mucin MUC5AC physically interacts with transmembrane protein CD44, in CRC cells, facilitates cancer progression via Src signaling, and confers chemoresistance through the β-catenin pathway." (PMID 32168759, 2020). "In the cases of SSA/Ps with carcinoma, MUC5AC immuno-expression was observed in 100% of SSA/Ps, in 62.5% of carcinoma, and irregularly in invasive carcinomas." (PMID 32168759, 2020).